MMP9 (matrix metallopeptidase 9)
Diseases named in the same sentence as MMP9 in open-access papers (continued):
Sharing a sentence is not in itself a finding about the gene and the disease.
glioma (449 papers, 2000 to 2026). A benign or malignant brain and spinal cord tumor that arises from glial cells (astrocytes, oligodendrocytes, ependymal cells). "Elevated serum MMP-9 values > 450.08 ng/mL were strongly associated with glioma cases compared to lower values (OR: 132.48, p < 0.01)." (PMID 40512281, 2025). "A significant elevation in the risk of glioma, with a 132.48-fold increase, was found at MMP-9 concentrations over the cut-off value." (PMID 40512281, 2025). "High levels of invasion and/or metastasis of cervical, colorectal, gastric, pancreatic, breast, and oral cancers, as well as gliomas and skin tumors, are typically linked to MMP-9 expression, which is strongly expressed in a wide range of malignancies." (PMID 38801618, 2024). "MMP2 is positively correlated with the invasion and migration of glioma cells, while MMP9 is implicated in cell invasion, migration and VM formation." (PMID 36459288, 2023). "MMP9 is associated with unfavorable prognosis of gliomas and is positively correlated with the grade of primary and recurrent gliomas." (PMID 36560848, 2023). "Inhibition of MMP-9 encouraged by mangiferin is associated with the suppression of glioma cell invasion." (PMID 38137424, 2023). "Among MMPs, MMP9 has been associated with the glioma grade and its upregulation to a poor prognosis." (PMID 36048342, 2022). "MMP-9 is a matrix metalloproteinase that regulates cell adhesion and is associated with the occurrence, progression and local invasion of gliomas." (PMID 35186504, 2022). "Consistent with our study of gliomas, MMP9 was identified as a hypoxia-driven gene associated with a poor outcome." (PMID 36118887, 2022). "Its overexpression correlates with increased invasive glioma grades, whereas a decrease of MMP-9 expression is associated with favorable outcome and response to Temozolomide treatment." (PMID 35221898, 2022). "The Kaplan–Meier survival analysis of our clinical samples showed that an overexpression of SCIN, MMP2, and MMP9 were associated with a poor prognosis of glioma patients, respectively." (PMID 36291348, 2022). "Altogether, our mRNA analysis in vitro and in vivo show that myeloid-cKO of CD44 severely hampers MMP9 upregulation in glioma-associated myeloid cells, and additionally affects levels of the pro-inflammatory cytokines." (PMID 35992852, 2022). "The overexpression of MMP-2 and MMP-9 was associated with various tumor progressions, including rectal cancer, glioma, and papillary thyroid carcinoma." (PMID 33959183, 2021). "MMP2, MMP9, and VE-cadherin are classic proteins associated with VM formation in glioma cells, and their high expressions suggest enhanced VM formation ability." (PMID 33542193, 2021). "Despite the controversy and known limitations of in vitro GBM cell culture, MMP9 has been proposed as a potential cancer biomarker, and its high expression is associated with poorer survival rates in glioma patients." (PMID 33919029, 2021). "Many studies have reported that high levels of TGF-β, EGF, MMP-2, MMP-9 and IL-10, and low levels of IL-12 can be produced by M2 polarized glioma-associated microglia/macrophages to promotes invasion, proliferation, immune evasion and angiogenesis of glioma." (PMID 34446611, 2021). "MMP-2 and MMP-9 are primarily associated with the invasiveness of high-grade gliomas, and MMP-2 activity in GBM was reported to be five-fold greater compared to normal brain or low-grade gliomas." (PMID 32545852, 2020). "MMP-9 is known to be overexpressed in gliomas, with higher expression associated with higher grade, and it can serve as both a biomarker and a predictor of survival in patients." (PMID 32258065, 2020). "FOXO3 promotes breast cancer cell invasion through the induction of MMP-9 and MMP-13 and has further been associated with MMP-9 activity and elevated invasion capacity in glioma, and with increased cell migration and invasion in gastric and colorectal cancer." (PMID 31861249, 2019).
glioma (continued). "MMP9 expression was associated with the World Health Organization (WHO) grade of glioma and induced glioma cell proliferation." (PMID 31284679, 2019). "FOXO3 has further been associated with MMP-9 activity and elevated invasion capacity in glioma, with increased cell migration and invasion in gastric and colorectal cancers." (PMID 31861249, 2019). "For example, STAT3 upregulated the expression of MT1E, the gene encoding metallotheonine-1E, which enhances human glioma cell migration and invasion by inducing the inactivation of MMP-9." (PMID 29774125, 2018). "This study further established that miR-146a suppresses tumorigenic gene, MMP9 in glioma-associated microglia and glioma cell viability through its target SMAD4." (PMID 29861845, 2018). "MMP-9 is another well-characterized enzyme and has been prominently implicated in glioma invasiveness." (PMID 27043542, 2016). "In tumor biology, it has been increasingly appreciated that MMP9 is associated with poor disease prognosis, such as glioma and gastric cancer." (PMID 25970782, 2015). "Expression of several candidate genes, such αvβ3 integrin and the matrix metalloproteinases, MMP-2, and MMP-9, in tumor cells has been reported to be associated with radiation-induced glioma cell invasion." (PMID 23940516, 2013). "In combination with miR-211 overexpression and inhibition of MMP-9, even the sublethal dose of ionizing radiation (5 Gy) was sufficient to cause significant disruption of neurospheres and DNA fragmentation in glioma stem cells." (PMID 23183822, 2012). "We also demonstrated that the ability of Bmi-1 to stimulate the invasive phenotype in glioma cells was mechanistically associated with activation of NF-kappaB and subsequent upregulation and activation of MMP-9." (PMID 22967049, 2012). "IHC analysis of 127 cases of clinical human glioma specimens revealed that upregulation of Bmi-1 was associated with in an upregulation of MMP-9 and nuclear localization of NF-kappaB." (PMID 22967049, 2012). "Numerous reports have mechanistically associated the invasive ability of glioma cells with expression and activation of MMP-9." (PMID 22967049, 2012). "Given the tumour-trophic associations between these mediators and P2X7R in glioma, decreased expression of IL-4, IL-8, MMP-9 and PCNA maybe compensatory in nature." (PMID 41034696, 2025). "The serum levels of MMP-9, for example, have been studied in the context of gliomas and have shown promise as a diagnostic marker that could differentiate between malignant and benign brain lesions." (PMID 40265458, 2025). "Notably, MMP-2 and MMP-9 have been associated with glioma invasiveness, while other MMPs, such as MMP-1 and MMP-7, are linked to metastatic gliomas." (PMID 40265458, 2025). "Although information about PEPD is limited, in several studies, the role of MMP-2 and MMP-9 has been underlined, e.g., finding positive correlations between MMPs levels and increasing grades of glioma malignancy associated with invasion, recurrences, poor prognosis, and shorter survival." (PMID 38275897, 2024). "Additionally, TLR2 expression is induced in glioma-associated macrophages (GAM) by glioma cells provoking the transcription of MMP-9 and MMP-14, and cancer growth and spread." (PMID 38069210, 2023). "Additionally, mangiferin appears to be linked to MMP-9 inhibition via initiating the suppression of glioma cells’ in vitro invasiveness." (PMID 38137424, 2023). "Furthermore, only TWEAK-treated glioma cells exhibited increased expression of integrins, as well as MMP9, all of which are associated cancer markers." (PMID 36945490, 2023). "Aberrant MMP-2 and MMP-9 activities have been implicated in the deterioration of glioma." (PMID 35012441, 2022). "In addition, in vitro tudies demonstrated that the suppression by ITCs of cell migration and invasion in C6 glioma cells was associated to inhibition of MMP-9 expression mediated by NF-κB." (PMID 33196947, 2021).
glioma (continued). "Furthermore, CSC invasion was markedly inhibited by an MMP9 inhibitor, validating the use of zebrafish models to study the mechanisms underlying the invasion and metastatic behavior of glioma cells." (PMID 33802571, 2021). "Indeed, MMP-9 expression has been associated with the degree of malignant glioma, and it is considered as a good predictor of invasive glioma cell growth." (PMID 31551765, 2019). "However, there are limited data regarding the association of PD-L1, MMP-9 and KI-67 expression in glioma." (PMID 28591697, 2017). "Due to its association with tumor invasion, we hypothesize that MMP-9/NGAL activity levels in urine could serve as marker of glioma tumor progression and patient prognosis before, during, and after therapy." (PMID 26663949, 2015). "The altered levels of the nine metabolites were closely associated with the changed functions of GFAP and MMP-9, suggesting that these metabolites could be explored as potential biomarkers for monitoring malignant transformation of glioma cells." (PMID 25163530, 2014). "Thus, we assume that the anti-proliferative, anti-invasive and apoptotic effect of miR-211 on glioma cells is associated with the downregulation of MMP-9 activity." (PMID 23183822, 2012). "Our results illustrated that the expression levels of MMP-2 and MMP-9 are associated with the pathological grades of the tumor, providing strong evidence that MMPs expression can be used as a criterion to determine the malignant phenotypes of gliomas." (PMID 23554622, 2010). "In addition, the expressions of SCIN, MMP2, and MMP9 were associated with glioma prognosis." (PMID 36291348, 2022). "In addition, the strong correlation of MUC4 and MMP9 expression with clinicopathological stage suggests both could serve as useful tissue diagnostic biomarkers in glioma patients." (PMID 36400876, 2022). "In addition, CCL2/CCL5, MMP-2, and MMP-9 have been implicated in TLR9-mediated glioma progression." (PMID 34715891, 2021). "Immunohistochemistry revealed strong MMP-9 expression in the neoplastic vessels of high-grade gliomas and cytoplasmic reactivity in meningiomas, with increased expression in atypical meningiomas (p = 0.036)." (PMID 40265458, 2025). "For example, certain polyphenols in green tea, such as epigallocatechin gallate (EGCG), have been shown to inhibit MMP-9 expression, reducing glioma cells’ invasiveness and angiogenesis in vitro." (PMID 40265458, 2025). "Their research underscores the critical roles of integrins, uPAR, and MMP9 in glioma tumor biology and proposes a possible interaction model between them." (PMID 40508119, 2025). "In the ROC analysis, the threshold values of the serum GAL-1, GAL-8, ITGβ-1, HIF-1α, and MMP-9 levels for diagnosing glioma were 41.83 ng/mL, 8.28 ng/mL, 436.34 pg/mL, 1411.00 pg/mL, and 450.08 ng/mL, respectively." (PMID 40512281, 2025). "Immunohistochemistry revealed MMP-2 positivity in 38% of glioma cases and MMP-9 positivity in 81%, with MMP-9 also observed in endothelial cells, suggesting its role in angiogenesis." (PMID 40265458, 2025). "Preclinical studies using siRNA or shRNA targeting MMP-2 or MMP-9 have shown that reducing these MMPs’ expression diminishes glioma cell invasion and enhances the response to chemotherapeutic agents." (PMID 40265458, 2025). "The diagnostic values of serum GAL-1, GAL-8, ITGβ-1, HIF-1α, and MMP-9 as a potential biomarker for gliomas were assessed using ROC curve analysis." (PMID 40512281, 2025). "In particular, MMP‐9 plays an essential role in the invasiveness of glioma cells because it directly degrades basal membrane and extracellular matrix proteins." (PMID 39791545, 2025). "Recent advances have shifted the focus toward isoform-selective inhibitors targeting specific MMPs that are critical to glioma progression, notably MMP-9 and MMP-14." (PMID 40265458, 2025).
glioma (continued). "High levels of MMP-2 and MMP-9 have been consistently correlated with increased invasiveness in high-grade gliomas, underscoring their importance in tumor spread." (PMID 40265458, 2025). "MMP-9, another gelatinase, is highly expressed in aggressive gliomas and contributes to invasion, immune suppression, and resistance to therapy." (PMID 40265458, 2025). "The gelatinases, MMP-2 and MMP-9, are thus of particular interest as biomarkers in assessing the progression of gliomas." (PMID 40265458, 2025). "MMP-9 expression is upregulated in glioma tissues, where it correlates with tumor grade, and its levels are significantly elevated in the serum of GB patients, suggesting its potential as a diagnostic marker for disease progression." (PMID 41154699, 2025). "MMP-9 plays a significant role in vasculogenic mimicry and tumor invasion, impacting glioma patient survival." (PMID 40284474, 2025). "Tenascin-C (TNC) promotes Akt phosphorylation, upregulating MMP-9 expression and facilitating vasculogenic mimicry and glioma invasion." (PMID 40284474, 2025). "MMP9 expression levels are increased in high-grade gliomas and are overexpressed in glioblastomas, while lower MMP9 expression correlates with improved patient survival." (PMID 40867242, 2025). "Ki67 and MMP9, markers of glioma proliferation and invasiveness, respectively, demonstrated higher expression in the Glioma group than in the Glioma + ML130 group, as evidenced by IHC." (PMID 41363048, 2025). "P2X7R was also upregulated in the glioma microenvironment and its expression was linked to the expression of VEGFB, MMP9, PCNA, IL-4 and IL-8." (PMID 41034696, 2025). "Blocking of MMP-9 expression with RNAi led to decreased invasiveness of glioma cells and increased response to chemotherapy." (PMID 41154699, 2025). "MMP-2, MMP-9, and MMP-14 are particularly implicated in BBB degradation in gliomas, where their activity weakens tight junctions between endothelial cells and facilitates tumor invasion into the brain parenchyma." (PMID 40265458, 2025). "An analysis of the mRNA expression profiles from multiple datasets revealed that MMP-9 expression was correlated significantly with the glioma grade and survival outcomes." (PMID 40265458, 2025). "The expression and activity of MMPs, particularly MMP-2 and MMP-9, are consistently elevated in aggressive gliomas, such as GBM, the most malignant form of glioma." (PMID 40265458, 2025). "MMP-2 and MMP-9 are particularly involved in the angiogenesis of human gliomas, as their degradation of ECM components releases stored pro-angiogenic factors, such as VEGF." (PMID 40265458, 2025). "Among MMPs, gelatinases MMP-2 and MMP-9 are the most extensively studied in various pathological conditions, such as diabetes, cardiovascular diseases, gliomas, and multiple cancers." (PMID 40724896, 2025). "Another study described the miR-885-5p interaction with matrix metalloprotease 9 (MMP9) in glioma cells." (PMID 40078479, 2025). "STAT3 and NF-ĸB have been found to directly regulate the expression of c-Myc and MMP9 in glioma cells." (PMID 40759869, 2025). "Previous studies have extensively documented the dysregulation and oncogenic properties of POSTN, CHI3L1, SAA1, and MMP9 in various cancer types, including gliomas." (PMID 39574472, 2024). "The relationship between the expression of Programmed cell death 1 ligand 1 (PD-L1) and VEGF, MMP-9, and KI-67 was studied earlier in glioma." (PMID 39062015, 2024). "Taken together, our evidence indicates that the predictive model constructed using POSTN, CHI3L1, SAA1 and MMP9 expression had significant prognostic value for patients with glioma." (PMID 39574472, 2024). "TMEM176A negatively regulates the invasive function of cells and it reduces the expression of MMP2, MMP9 in different types of tumors, such as glioma, colorectal, liver, and esophageal cancers." (PMID 38850316, 2024).
glioma (continued). "Overexpression of MAGI1 can affect AKT, MMP2, and MMP9 and inhibit the invasion and migration of glioma cells." (PMID 39458959, 2024). "The results of this study suggest that the knockdown of TBC1D1 affects the downstream expression of MMP2 and MMP-9 and inhibits the invasiveness of glioma cells." (PMID 38189823, 2024). "MMP-2 and MMP-9 are extracellular proteolytic enzymes participating in the invasion and tumor progression of glioma, and our results showed significant P129-induced MMP-2 and MMP-9 inhibition." (PMID 38184514, 2024). "MMP-2 and MMP-9 levels were reduced by the downregulation of B7-H6 expression in glioma and B-cell NHL." (PMID 39408655, 2024). "The genes POSTN, CHI3L1, SAA1, and MMP9 were screened to establish a predictive model, which exhibited a significant correlation with glioma prognosis and served as independent prognostic factors." (PMID 39574472, 2024). "Previous studies have indicated that MMP9 can be secreted by M2 macrophages within the glioma tissue microenvironment, thereby promoting cellular invasion." (PMID 39574472, 2024). "For example, Diaph1 knockdown suppress migration and reduces the expression of matrix metallopeptidase MMP2 and MMP9 in human glioma cells." (PMID 39010074, 2024). "The expression levels of POSTN, CHI3L1, SAA1, and MMP9 were assessed in various glioma cell lines (U87, U251, U118, A172, T98G, SF295, LN229, and SF126) using qRT-PCR." (PMID 39574472, 2024). "To ensure accuracy, we compared the gene expressions of POSTN, CHI3L1, SAA1, and MMP9 in these glioma cells using the CCLE database and confirmed that the classification was consistent." (PMID 39574472, 2024). "This interaction between CD44 and MMP9 facilitates glioma cell migration, which was also found to be highly enriched in mediating signal transduction in our study." (PMID 39033204, 2024). "The level of miR-16 inversely correlates with NF-κB 1 protein expression, and miR-16 directly reduces the expression of the NF-κB 1 protein, inhibiting glioma cell invasion through the NF-κB/MMP9 signaling pathway." (PMID 37509289, 2023). "ROBO1 knockdown suppressed the expression of matrix metallopeptidase 2 (MMP2) and matrix metallopeptidase 9 (MMP9), thereby inhibiting the invasive, migratory and VM-forming abilities of glioma." (PMID 36459288, 2023). "They discovered that the delocalisation of the MMP-9 signal from glioma cells to endothelial cells of neoplastic blood arteries is directly associated with tumour malignancy." (PMID 36765669, 2023). "MMP-9 agonist as well as anti-miR-15b decreases the restorative effects of mangiferin in the glioma cells." (PMID 38137424, 2023). "Nobiletin (425 μM or 4 mg/ml) can inhibit the expression of MMP-2 and MMP-9 in glioma cells and reduce the motility, adhesion and invasion ability of glioma cells." (PMID 37932838, 2023). "In vitro glioma experiments showed that the inhibition of cathepsin B resulted in the downregulation of MMP-9 and VEGF expression." (PMID 37398678, 2023). "Second, GAMs also secrete matrix metallopeptidase 2 (MMP2) and MMP9, which are able to breakdown matrix proteins, such as collagen and fibronectin, thereby enabling glioma cells to penetrate and invade the surrounding stromal tissues." (PMID 38130720, 2023). "scRNA-Seq of s.c. and i.c. mouse gliomas demonstrated in both models that macrophage PP2Ac deficiency upregulates Type I IFN-activated macrophages and downregulates high MMP9/oxidative phosphorylation macrophages." (PMID 36757811, 2023). "Simultaneous RNAi-mediated targeting of MMP-9 and cathepsin B has potential application in the treatment of human gliomas." (PMID 36980765, 2023). "The expression of MMPs, especially MMP2, and MMP9, is upregulated and correlated with progression, tumor aggressiveness, and poor prognosis in glioma." (PMID 37509289, 2023).